APC (APC regulator of Wnt signaling pathway)
Diseases named in the same sentence as APC in open-access papers (continued):
Sharing a sentence is not in itself a finding about the gene and the disease.
Familial adenomatous polyposis (continued). "Germline adenomatous polyposis coli (APC) mutations represents the genetic basis of familial adenomatous polyposis (FAP); more than 60% of sporadic CRC cases have genetic alterations in the APC gene leading to stimulation of the Wnt/β-catenin pathway, which drives tumor initiation and recurrence." (PMID 30736475, 2019). "The APC locus was discovered by studying a rare hereditary syndrome, familial adenomatous polyposis (FAP)." (PMID 31614493, 2019). "Loss of function in APC gene leads to the development of adenomas, a precursor lesion to CRC, in familial adenomatous polyposis (MIM #175100)." (PMID 30809968, 2019). "In addition, a number of factors substantially increase the risk of developing CRC, including inherited mutations in APC, such as Familial Adenomatous Polyposis (FAP)." (PMID 30405205, 2018). "Apart from the dysregulated expression of non-coding RNAs, the hypermethylation of APC, the gene responsible for familial adenomatous polyposis, occurs frequently in parathyroid adenomas although aberrant APC expression has not been demonstrated." (PMID 30598042, 2018). "The APC was initially identified as the main cause of familial adenomatous polyposis (FAP) syndrome; thereafter it was reported that the genes encoding APC are commonly mutated in most sporadic colorectal cancers." (PMID 30150508, 2018). "Approximately 30% of patients have tumors related to Familial Adenomatous Polyposis (FAP), including those with a mutation on the APC gene." (PMID 29879959, 2018). "Patients with Familial Adenomatous Polyposis (FAP), Gardner’s syndrome, and Turcot’s syndrome who carry a mutation in the APC gene have an increased risk of thyroid cancer, resulting in inappropriate Wnt pathway signaling." (PMID 29642644, 2018). "APC and MUTYH genes are mutated in 70–90% and 10–30% of familial adenomatous polyposis cases (FAP) respectively." (PMID 29954149, 2018). "Familial adenomatous polyposis (FAP) is an inherited condition arising from genetic defects in the Adenomatous polyposis coli (APC) gene." (PMID 30256815, 2018). "Germline mutations of the APC gene cause familial adenomatous polyposis (FAP)." (PMID 28423518, 2017). "Germline mutations in the APC gene are responsible for familial adenomatous polyposis (FAP), however, somatic mutations in APC occur in 80% of sporadic colorectal tumors." (PMID 28989593, 2017). "Here, a thorough review was carried out on the role of TSGs with the focus on the APC as the master regulator, mutated genes and mal-/dysfunctional pathways that lead to one type of hereditary form of the CRC; namely familial adenomatous polyposis (FAP)." (PMID 28331559, 2017). "APC was discovered by genetic linkage analysis in familial adenomatous polyposis (FAP) and was reported by Kinzler, Nishisho, Joslyn and Groden." (PMID 28515349, 2017). "Mutation of APC gene is implicated in the pathogenesis of familial adenomatous polyposis (FAP)." (PMID 28851389, 2017). "The variant was found in a patient (III:61) with unexplained familial adenomatous polyposis (1–100 polyps), this patient also had a VUS, APC c.4472T > A, p.Phe1491Tyr." (PMID 27696107, 2017).
Familial adenomatous polyposis (continued). "Two SPNs have been reported in patients with Familial Adenomatous Polyposis (FAP), caused by germline APC mutations, confirming that an APC mutation is also capable of driving SPN development." (PMID 27267993, 2016). "Probably the most famous example is the hereditary colon cancer known as Familial Adenomatous Polyposis (FAP), which results from germline mutations in the Adenomatous Polyposis Coli (APC) gene." (PMID 27438854, 2016). "Although usually sporadic it may occur in association with familial adenomatous polyposis (FAP), or Gardner syndrome caused by germline mutations in the APC gene." (PMID 27891213, 2016). "Familial adenomatous polyposis (FAP) is a syndrome with mutations in APC gene on 5q21–q22." (PMID 27087812, 2016). "Although Lynch syndrome and familial adenomatous polyposis (FAP), caused by inherited germline mismatch repair (MMR) and APC gene mutations respectively, contribute significantly to CRC a genetic diagnosis cannot be obtained in over 50 % of familial cases." (PMID 27356891, 2016). "Desmoid tumors occur at a rate of 10-15% in patients with Familial Adenomatous Polyposis (FAP), an autosomally inherited disease caused by germline mutations in the APC gene." (PMID 26889339, 2015). "A pig model for the human familial adenomatous polyposis was generated by inactivation of the adenomatous polyposis coli (APC) gene." (PMID 26442109, 2015). "Meanwhile, defects in the APC gene cause familial adenomatous polyposis (FAP), an autosomal dominant pre-malignant disease that usually progresses to malignancy, suggesting that APC could be a potential predictor for cancer initiation or development." (PMID 24661338, 2014). "While germline mutations in the APC gene are responsible for familial adenomatous polyposis (FAP), somatic mutations in APC occur in ~90% of sporadic colorectal tumors." (PMID 24995503, 2014). "In addition, there is an increased risk for colorectal cancer associated with mutations in the APC (familial adenomatous polyposis [FAP] or attenuated-FAP) and MUTYH (MUTYH-associated polyposis) genes." (PMID 25204323, 2014). "Most desmoid tumors arise sporadically, with a minority associated with familial adenomatous polyposis (FAP), which is caused by a germline mutation of the adenomatous polyposis (APC) gene." (PMID 24788118, 2014). "familial adenomatous polyposis (FAP) is the most common and it is an as autosomal dominant transmission due to mutation in the APC genes, and the endoscopy picture is so typical of hundreds of polyposis." (PMID 23737765, 2013). "APC (adenomatous polyposis coli) is located on chromosome 5 in the q21 region and contains 21 exons." (PMID 24148210, 2013). "Familial adenomatous polyposis (FAP), characterized by the development of numerous premalignant colorectal adenomatous polyps, is caused by a germline mutation in the tumor suppressor adenomatous polyposis coli (APC) gene." (PMID 24245549, 2013). "It was first suggested that NSAIDs inhibited Wnt signaling when sulindac was used to treat familial adenomatous polyposis (FAP, a disease caused by inactivating mutations in the Wnt inhibitor APC) to reverse polyp growth." (PMID 24212796, 2011). "Mutations in APC are responsible for most of the cases of familial adenomatous polyposis (FAP)." (PMID 21858148, 2011). "Activation of the APC/β-catenin/TCF pathway is an initiating event of neoplasia in familial adenomatous polyposis patients." (PMID 21970873, 2011). "Patients with familial adenomatous polyposis (FAP), due to a germ-line mutation in one allele of the tumor suppressor gene adenomatous polyposis coli (APC), have a near 100% risk of developing CRC by the age of 40 if untreated." (PMID 24213116, 2011). "Mutations in APC have also been associated with chromosomal instability and aneuploidy in early polyps from FAP (Familial Adenomatous Polyposis) patients." (PMID 20368985, 2010).
Familial adenomatous polyposis (continued). "Familial adenomatous polyposis (FAP) is an autosomal dominant-inherited colorectal cancer syndrome, caused by germline mutations in the APC gene." (PMID 19531215, 2009). "Another autosomal dominant disease, Familial Adenomatous Polyposis (FAP), is caused by a germline mutation in the APC gene, and confers a near 100% risk of developing CRC." (PMID 19506731, 2008). "While the majority of DTs arise sporadically, approximately 10–15% may be associated with familial adenomatous polyposis (FAP), involving mutations in the Adenomatous Polyposis Coli (APC) gene." (PMID 41228263, 2025). "Familial adenomatous polyposis (FAP), arises from APC germline mutations." (PMID 40695959, 2025). "Accordingly, somatic APC mutations represent an early event occurring in 85% of sporadic colorectal cancer (CRC), while germline mutations are responsible for the CRC-predisposing syndrome familial adenomatous polyposis (FAP)." (PMID 39519079, 2024). "Familial adenomatous polyposis (FAP) is an autosomal dominant colorectal cancer predisposition syndrome, typically characterized by the presence of numerous (ranging from hundreds to thousands) polyps in the epithelium of the large intestines caused by germ line mutations in the APC gene." (PMID 39021676, 2024). "Intra-abdominal DT are rare and may often represent genetically determined lesions, occurring as an extracolonic manifestation of familial adenomatous polyposis (FAP), especially Gardner syndrome, which are associated with a germline mutation in the APC gene." (PMID 35913675, 2023). "Familial adenomatous polyposis syndrome (FAP), which is characterized by multiple polyp formations in the gastrointestinal tract, is caused by a germline mutation in the adenomatous polyposis coli (APC) gene." (PMID 36765950, 2023). "For example, individuals with familial adenomatous polyposis (FAP), associated with truncating germline mutations in APC, or with Lynch syndrome, associated with germline mutations in DNA mismatch repair (MMR) genes, experience a higher incidence of CRC, and disease onset at an earlier age." (PMID 37542051, 2023). "Around 85–90% of desmoid tumors are sporadic, associated with mutations in the CTNNB1 gene, which encodes β-catenin, and 5–10% develop in the context of familial adenomatous polyposis (FAP), in which a germline mutation of the adenomatous polyposis coli (APC) gene is detected." (PMID 37568749, 2023). "Finally, patients with familial adenomatous polyposis (FAP), a CRC predisposition syndrome caused by germline mutations in the APC gene, rapidly develop large numbers of polyps and the average age of cancer onset in untreated patients is 40 years." (PMID 36040985, 2022). "Similarly, those with germline inactivation of the APC gene, associated with familial adenomatous polyposis (FAP), have a 4.5% lifetime risk of developing SBA, while those with an inherited STK11 mutation, resulting in Peutz-Jeghers syndrome (PJS), have a relative risk of 520 for developing SBA." (PMID 35267592, 2022). "Mutations in the APC occur early in colorectal tumorigenesis and not only are responsible for familial adenomatous polyposis, but also play a role in the majority of non-inherited sporadic colorectal cancer." (PMID 33807577, 2021).
Familial adenomatous polyposis (continued). "Familial adenomatous polyposis (FAP) results from a genetic defect in the APC gene." (PMID 34503225, 2021). "Familial adenomatous polyposis (FAP), which has an increased risk of CRC progression, is mainly caused by APC gene mutation, which may account for 87% and which are causative point mutations, while 10%–15% of them are intragenic deletions and duplications." (PMID 34638601, 2021). "Of note, APC and KRAS, genes that are mutated early in colon adenoma–carcinoma progression, were dominantly mutated in MSC-2, which implies that familial adenomatous polyposis (FAP) may be one of the main causes of MSC-2." (PMID 33959500, 2021). "Familial adenomatous polyposis (FAP) is an autosomal-dominant condition characterized by the presence of multiple colorectal adenomas, caused by germline variants in the adenomatous polyposis coli (APC) gene." (PMID 33670908, 2021). "Pilomatricomas have been described in a few patients with APC-mutated familial adenomatous polyposis (Gardener syndrome) but APC-mutations have not been reported in non-syndromic pilomatricoma." (PMID 32155193, 2020). "For example, a physician or genetic counselor may recommend carrier testing of a prospective parent for a mutation in the CFTR gene associated with cystic fibrosis or testing for mutations in the APC gene for a member of a family with a history of familial adenomatous polyposis (FAP)." (PMID 32342786, 2020). "The missense variant c.289G>A, p.(Gly97Arg) in APC was identified in two siblings (no. #14;16 and #14;20) with attenuated familial adenomatous polyposis (AFAP) phenotype." (PMID 33193653, 2020). "Genetic analysis revealed an absence of mutations on the APC gene, excluding syndromes like familial adenomatous polyposis (FAP), attenuated FAP and Gardner syndrome." (PMID 30953464, 2019). "These deleterious APC mutations mostly occur in a specific region, the APC mutation cluster region (MCR), and singularly define Familial Adenomatous Polyposis (FAP), a genetic condition predisposing to the development of colorectal adenomatous polyps and early onset colorectal adenocarcinoma." (PMID 31231471, 2019). "Rare germline APC missense mutations are not part of the typical mutation spectrum of APC-related familial adenomatous polyposis (FAP)." (PMID 30680046, 2019). "A common murine model of familial adenomatous polyposis - featuring a deletion of the APC gene - develop spontaneous adenomas in the colon, although these lesions may not fully exhibit the physiological features of the disease as seen in humans." (PMID 31072353, 2019). "Inversion prone position effects are not only limited to other species, it has also been reported in some human disease conditions, such as aniridia (PAX6), campomelic dysplasia (SOX9), familial adenomatous polyposis (APC) and Saethre-Chotzen syndrome (TWIST1)." (PMID 31191618, 2019). "We sought to develop a novel approach based on the generation of induced pluripotent stem cells (iPSC) from normal individuals or from patients with familial adenomatous polyposis (FAP), the second most highly penetrant form of hereditary CRC, which is caused mainly by APC mutations." (PMID 30024920, 2018). "Among them, one of the most important drivers of CRC is Adenomatous Polyposis Coli (APC) as more than 50% of hypermutated tumors and more than 80% of non-hypermutated tumors have mutations in APC." (PMID 30024920, 2018). "Current guidelines recommend initiation of colonic surveillance at age 10 to 12 for those with a genomic APC mutation consistent with profuse and intermediate polyposis (also called classic FAP) and in the late teens for attenuated familial adenomatous polyposis (AFAP)." (PMID 30012100, 2018).
Familial adenomatous polyposis (continued). "In agreement with the concept of eventual regional variants and/or population heterogeneity, we have previously reported novel mutations in other genes in our population, detected by direct sequencing such as protooncogen RET, Lynch Syndrome, APC in Familial Adenomatous Polyposis." (PMID 28947987, 2017). "CRC: colorectal carcinoma; NS: non significant; APC: adenomatous polyposis coli." (PMID 27462886, 2016). "CRCs with chromosomal instability frequently demonstrate loss of heterozygosity (LOH) involving numerous genes, but particularly the APC (Adenomatous Polyposis Coli) and DCC (Deleted in Colorectal Cancer) genes, as well as point mutations in the KRAS (Ki-ras2 Kirsten rat sarcoma) gene." (PMID 26970738, 2016). "The possibility of adenomatous polyposis coli (APC) syndrome is remote in this case because the polyposis is not constituted and no APC gene mutation analysis was performed." (PMID 27087812, 2016). "Familial adenomatous polyposis (FAP) is an autosomal dominant hereditary colon cancer syndrome characterized by 100 or more premalignant polyps caused by germline mutations in the tumor suppressor gene, adenomatous polyposis coli (APC), located on chromosome 5q21-q22." (PMID 27777639, 2016). "In addition, in familial adenomatous polyposis (FAP), patients who inherit a germline mutation in the APC gene, the lifetime risk of developing CRC approaches 100%." (PMID 24179534, 2013). "The Pirc rats have mutated APC gene thus not just genetically recapitulating human disease such as familial adenomatous polyposis but also most sporadic colonic neoplasia." (PMID 23049818, 2012). "After data from approximately 40 observational studies demonstrated the utility of COXIBs as chemopreventive agents in patients with familial adenomatous polyposis, three randomised trials with similar designs (APPROVe, APC, and PreSAP) were launched between 1999 and 2000." (PMID 22649288, 2012). "Neither genetic testing for the Adenomatous Polyposis Coli (APC) gene mutation nor screening with colonoscopy for adenomatous polyposis coli or colorectal cancer was performed." (PMID 21426541, 2011). "Although usually sporadic it may occur in association with familial adenomatous polyposis (FAP) in which case it is termed Gardner's syndrome and is linked to germline mutations in the APC gene." (PMID 20634933, 2010). "For example, in familial adenomatous polyposis (FAP), affected persons carry different germline mutations in the APC gene and are prone to developing cancers of the colon and the rectum—and, less frequently, cancers in other tissues such as stomach, liver, and bones." (PMID 20084116, 2010). "Furthermore, 7.3%–20% of cases with colorectal adenomatous polyposis involve somatic APC mosaicism." (PMID 41214301, 2026). "A study on familial adenomatous polyposis (FAP), an inherited condition, found that nearly all human adenomas exhibited YAP activation following APC deficiency, indicating that YAP is crucial for the development of these adenomas in FAP patients." (PMID 39977302, 2025). "In cases of Familial Adenomatous Polyposis (FAP), a truncated APC protein with low affinity to β-catenin is created, resulting in the nuclear accumulation of β-catenin and consequently, overexpression of its target genes." (PMID 35913675, 2023). "Only germline single-nucleotide variants located in the promoter 1B of the APC gene are responsible for GAPPS, currently recognized as a gastric-restricted variant of familial adenomatous polyposis (FAP)." (PMID 37239438, 2023).